TLR3 (toll like receptor 3)
Diseases named in the same sentence as TLR3 in open-access papers (continued):
Sharing a sentence is not in itself a finding about the gene and the disease.
cancer (continued). "PolyI:C, a synthetic double-stranded RNA molecules which targets the MDA-5/RIG-I pathway and TLR3 has been studied for many years as a standalone cancer therapy or vaccine adjuvant." (PMID 40280970, 2025). "Our findings reveal a new way by which nucleus-localized TLR3 contributes to chemoresistance and poor prognosis of cancer via interactions with oncogenic PRMT5 and c-Myc in the nucleus." (PMID 40675966, 2025). "Meanwhile, mice bearing cancer cells with nuclear TLR3 exhibited increased liver metastasis and shortened survival." (PMID 40675966, 2025). "Unexpectedly, we found nuclear localization of TLR3 in cancer cells, but barely in the corresponding normal cells." (PMID 40675966, 2025). "While TLR3 activation can induce apoptosis in some cancer cells, research has unveiled a more intricate role in tumorigenesis." (PMID 40647457, 2025). "Nuclear TLR3 increased the invasive and proliferative properties, and inhibited chemotherapy-induced apoptosis of cancer cells in vitro." (PMID 40675966, 2025). "As more clinical trial data become available, these findings will provide critical insights into the integration of TLR3 agonists in future cancer therapies." (PMID 39988665, 2025). "IL-33 induced by TLR3/4-TBK1-IRF3 signaling pathways drives cancer-prone chronic inflammation in the skin and pancreas." (PMID 40579434, 2025). "All our IHC results undoubtedly demonstrate that TLR3 expression co-localizes with cancer stem markers (CD133 and ALDH1) and tested DAMPs (RAGE and HSP70)." (PMID 40647457, 2025). "Consistent with mouse studies, these clinical data demonstrate a correlation between elevated nuclear TLR3 expression in cancer cells and the increased progression, chemoresistance, poor prognosis of cancer patients." (PMID 40675966, 2025). "Why dsRNA accumulates in the nucleus and how TLR3 interacts with nuclear dsRNA in cancer cells requires future analysis." (PMID 40675966, 2025). "Toll-like receptor 3 (TLR3) plays a complex role in cancer, exhibiting both pro-apoptotic and pro-tumorigenic effects." (PMID 40647457, 2025). "In this study, we report that TLR3, a traditionally membrane-associated PRR in the cytoplasm, translocates to the nucleus of cancer cells, in particular under chemotherapeutic stress." (PMID 40675966, 2025). "Poly ICLC, a stable and potent derivative of Poly I: C, which acts as a TLR3 agonist, is extensively researched as an adjuvant in cancer immunotherapy clinical trials." (PMID 39988665, 2025). "We found an obvious reduction in the number of apoptotic TLR3 knockout cancer cells, compared to control cancer cells." (PMID 40675966, 2025). "Collectively, nucleus-localized TLR3 promotes cancer cell proliferation, invasion and contributes to chemoresistance by inhibiting cancer cell apoptosis." (PMID 40675966, 2025). "TLR3 activation with Poly I: C can induce breast cancer cells to express phenotypes of cancer stem cells (CSCs) that possess tumorigenic properties." (PMID 39988665, 2025). "TLR3 agonists hold great promise in cancer immunotherapy, but their dual role in cancer pathogenesis complicates the safety and efficacy of systemic administration." (PMID 39988665, 2025). "Accordingly, high levels of cancer cell nuclear TLR3 in clinical samples predicted patients’ worse prognosis with shorter disease-free survival, overall survival and poor response to neoadjuvant chemotherapy." (PMID 40675966, 2025). "Poly(I:C), a Toll-like receptor 3 (TLR3) agonist, has been explored as an adjuvant in cancer immunotherapy." (PMID 41154585, 2025). "Nevertheless, the pro-inflammatory nature of the TLR3 pathway laid the foundation for the development of TLR3 agonists in cancer immunotherapy." (PMID 39988665, 2025). "To explore the immune signaling pathways affected by TLR3, we reviewed the literature and found that NF-κB signaling essential for immune responses, inflammatory response and cancer therapy." (PMID 40406122, 2025).
cancer (continued). "Our results after MAVS knockdown suggest that either RIG-I or MDA5 is involved in the CXCL10 secretion by cancer cells and that the TLR3 pathway contributes at least as much to CXCL10 secretion as the MAVS pathway." (PMID 40029556, 2025). "Toll-like receptor 3 (TLR3) is a pattern recognition receptor known to play a crucial role in the immune response to cancer." (PMID 40406122, 2025). "We aim to investigate the role of TLR3 in the production and secretion of DAMPs, and how these DAMPs influence cancer stem cells (CSCs)." (PMID 40647457, 2025). "In cancer, TLR3 signaling can activate pro-survival pathways, reprogram cellular metabolism, and contribute to the establishment of a supportive microenvironment for metastasis, thereby fostering malignant progression." (PMID 40647457, 2025). "There was a significant reduction in cellular migration of U87 cancer cells at TLR3 and TLR4 preconditioning." (PMID 38698968, 2024). "Given that the gut virome, composed of various viruses residing in the gut, can interact with host immune pathways like TLR3, there is potential for these viral communities to influence cancer immune responses and treatment efficacy." (PMID 39791120, 2024). "Several nucleic acid-based TLR3 agonists have been explored clinically as vaccine adjuvants in cancer and infectious disease, but present substantial manufacturing and formulation challenges." (PMID 38659926, 2024). "In situ vaccination (ISV) combining Flt3L, local radiotherapy, and a TLR3 agonist, led to systemic clinical cancer remission and potentiation of PD-1 blockade in patients with advanced stage indolent non-Hodgkin’s lymphomas (iNHLs)." (PMID 38926350, 2024). "Therapeutic cancer vaccination using TLR3 agonists, such as PolyICLC, are also currently under investigation in patients with advanced cancer including BC (NCT02643303)." (PMID 38433837, 2024). "Such specificity and ability to enhance anti-tumor responses, especially in conjunction with PD-1/PD-L1 blockade, underscore the therapeutic promise of TLR3 agonists in cancer treatment." (PMID 38732254, 2024). "TLR3 stimulation induced cancer growth under low serum conditions and metabolic switch from oxidative phosphorylation to extra-mitochondrial glycolysis in a HIF-1α dependent mechanism." (PMID 36982351, 2023). "For instance, FADD, FASLG, RIPK1, RIPK3, and TNF were more prone to copy number gain than loss in pan-cancer, but FAS and TLR3 displayed the reverse tendency." (PMID 37351504, 2023). "In this context, new studies are needed to better understand the link between TLR3-induced cancer cell death and immune system activation." (PMID 37275475, 2023). "Amid all the TLR ligands TLR3, 7, 8, and 9 mediated signaling demonstrated a significant role in cancer biology." (PMID 37936697, 2023). "TLRs, except for TLR3, mediate the downstream signaling through MyD88, a adaptor protein that ubiquitously expressed in all the immune cells and several cancer tissues." (PMID 37822929, 2023). "It is also consistent with our findings that the three samples of the necrotic fluid with the highest levels of TLR3 stimulation were from patients with very aggressive cancers." (PMID 37894949, 2023). "ERV-derived dsRNA produced by cancer cells has also been suggested to activate TLR3 in endothelial cells in mouse cancer models." (PMID 36630597, 2023). "Among them, TLR3 senses endosomal double-stranded RNA (dsRNA) and is expressed in a variety of cell types including epithelial and immune cells, and cancer cells of several histotypes." (PMID 37275475, 2023). "They induce both inflammatory apoptosis in cancer cells and activation of myeloid cells, and therefore represent useful tools to explore the role of TLR3 in cancer therapy." (PMID 37275475, 2023).
cancer (continued). "The self-dsRNA initiates type I interferon response consisting of IFNα, IFNβ, and CXCL10 by binding TLR3 on cancer cells in a paracrine manner." (PMID 36979348, 2023). "In this context, TLR3 has been found to play an immunosuppressive role in the progression of cancer and survival, but its overexpression leads to increased metastasis." (PMID 37822929, 2023). "Altogether, these results show that TL-532 induces TLR3-mediated inflammation in both myeloid and cancer cells, and TLR3-mediated immunogenic cell death through apoptosis in cancer cells." (PMID 37275475, 2023). "In this respect, our results extend previous findings documenting a crucial role of TLR3 signaling in type I IFN release by cancer cells." (PMID 36964168, 2023). "In contrast, we and others have shown that under various experimental conditions, TLR3 activation can also promote cancer cell metabolic reprogramming, proliferation, migration and invasiveness." (PMID 37894949, 2023). "In another study, we have demonstrated that, besides metabolic changes, TLR3 activation increases cancer cell migration, ROS production, and decreases anti-oxidative response." (PMID 36982351, 2023). "In non-small-cell lung cancer (NSCLC), the expression of TLR3 on cancer cells contributed to stimulated CD103+ lung dendritic cell subset, activated caspase-3 and induced apoptosis." (PMID 35413927, 2022). "In fact, with the deepening of research, the effect of TLR3 tends to be a “two-side effect”, that is, TLR3 can promote and inhibit cancer at the same time." (PMID 35664309, 2022). "Previous studies on TLR3 were mainly focused on infectious diseases and inflammation-related diseases, but there were few studies on cancers." (PMID 36419829, 2022). "Cancer cells with higher TLR3 expression were more sensitive to JNJ-42756493 and IPI-145, but they were correlated with increased drug resistance to tyrothricin." (PMID 35165523, 2022). "TLR3 stimulation has been reported to promote BC cells toward a cancer stem cell phenotype and, notably, an increased TLR3 expression in BC patients is shown to have a poor prognosis." (PMID 35740335, 2022). "At the same time, we studied the interacting genes and related functions of TLR3 in order to understand the possible mechanisms of TLR3 affecting cancers." (PMID 36419829, 2022). "TLR3 stimulation promoted metabolic reprograming in cancer cells, switching oxidative phosphorylation to anabolic glycolysis (through upregulation of HIF-1α) and enabling better adaptation to hypoxia and oxidative stress in the TME." (PMID 35884895, 2022). "Among them, HIV TAR RNA promotes cancer cell proliferation and induces the expression of proto-oncogenes and Toll-like receptor 3 (TLR3)-inducible genes." (PMID 35884611, 2022). "The mRNA expression of the same necroptosis-related regulator was upregulated in one cancer type but downregulated in another cancer type, such as TLR3 in KIRC and LUSC." (PMID 35748782, 2022). "For the sake of further exploring the possible mechanisms of TLR3 affecting the prognosis of cancers, we also explored the correlations of TLR3 expression with the immune cells infiltration levels in KIRC, LGG and PAAD." (PMID 36419829, 2022). "Correlation analysis indicated that the mRNA expression levels of necroptosis-related regulators were positively correlated with their copy number levels in most cancers, such as TLR3 in LIHC." (PMID 35748782, 2022). "First of all, we explored TLR3 expression levels in multiple cancers using GEPIA and TIMER databases." (PMID 36419829, 2022). "For instance, polyinosinic/polycytidylic acid (PolyIC), a well-known dsRNA analog, have shown efficacy in cancer immunotherapy through Toll-like receptors 3 (TLR3) triggered innate immune and entered clinical trials." (PMID 34466734, 2022). "As a ligand to TLR3, Poly(I:C) has been widely utilized as a vaccine adjuvant or combined with antibodies for immunotherapies against various cancers." (PMID 35890342, 2022).
cancer (continued). "TLRs are key molecules involved in inflammation‐driven cancer and all of them, except TLR3, commonly use MYD88 as the downstream adapter protein leading to activation of NF‐κB signalling." (PMID 36433652, 2022). "TLR3 can play an anti-cancer role by regulating downstream signaling that enhances expression of pro-inflammatory cytokines, chemokines, and interferons." (PMID 34769259, 2021). "The expression of TLR3 in cancer cells seems to be quite common, but the roles and molecular mechanism of TLR3 in cancers are quite complicated." (PMID 33986756, 2021). "In cancer cells only, TLR3 acquires death receptor properties by efficiently triggering the extrinsic pathway of apoptosis with Caspase-8 as apical protease." (PMID 34011952, 2021). "For example, synthetic cancer neoantigen long peptide vaccines formulated with a toll-like receptor 3 (TLR3) ligand poly-ICLC (polyinosinic and polycytidylic acid) induced strong anti-cancer immunity and clinical response." (PMID 34579759, 2021). "The dsRNA TLR3 agonists, Ampligen (Rintatolimod) and Hiltonol, also have well described adjuvant properties, with Hiltonol being tested in therapeutic cancer vaccine trials (ClinicalTrials.gov Identifier: NCT04345705 and NCT02423863)." (PMID 33439897, 2021). "Studies have also shown that TLR3 is expressed on cancer cells and its activation leads to recruitment of different leukocyte subpopulations." (PMID 33633150, 2021). "To determine the differential expression of TLR3, we analyzed the data from the cancer genome atlas (TCGA) by TIMER and found that TLR3 was significantly decreased in LUAD tissues than in adjacent lung tissues." (PMID 34094905, 2021). "Similar to TLR3 and TLR7, TLR9 is expressed on endosomal membranes of several immune cells, and it has been linked to acute pancreatitis and cancer." (PMID 34884547, 2021). "The findings elucidated herein will provide valuable insights into understanding the TLR3-mediated adjuvant therapy in cancer." (PMID 33072559, 2020). "TLR3 synthetic ligands were used with conventional chemotherapies or radiotherapy in clinical trials for the treatment of cancer patients." (PMID 33072559, 2020). "This unusual function of tumoral TLR3 has increased clinical interest in its targeting, prompting efforts to exploit the direct apoptotic effects of TLR3 on cancer cells." (PMID 32093313, 2020). "Particularly, various TLR3 agonists are being used in cancer treatments, and interest in these TLR3 agonists in clinical use as adjuvant for the activation of immune system is constantly growing." (PMID 32093313, 2020). "A deeper characterization of the complex and bidirectional cross-talk between TLR3-expressing cancer cells and immune populations is thus required to define TLR3 feasibility both as a prognostic marker and therapeutic target." (PMID 32093313, 2020). "TLR3-mediated mechanism of apoptosis in cancer cells is dependent on caspase-8 activation, which activates caspase-3 by proteolytic cleavage to amplify caspase-8 apoptosis initiation signals." (PMID 32093313, 2020). "Accordingly, a mechanism scheme of alternative TLR3 signal transduction responsible for the proliferation of the cancer cells has been presented." (PMID 33072559, 2020). "TLR3, like other TLRs, is also expressed on epithelial cells, including cancer cells of several histotypes." (PMID 32093313, 2020). "In the case of TLR3, Poly (I:C) is a TLR3 ligand that functions as a potent adjuvant for cancer vaccines; however, due to its fast degradation, new alternative agonists are being investigated." (PMID 32984007, 2020). "Our results are corroborated by a case-control study comparing cervical biopsies from healthy and carcinoma samples, where a reduction of TLR3 expression—both at mRNA and protein levels—was found in the presence of HPV." (PMID 33013878, 2020). "Various types of cancers can be treated with TLR3 agonists as an adjuvant therapy with other vaccines or drugs." (PMID 31480568, 2019).
cancer (continued). "In such scenario, we investigated the expression of TLR3 on both cancer and immune compartments in early stage NSCLC, highlighting opposing prognostic functions of this receptor." (PMID 31582772, 2019). "The prognostic significance of TLR3 expression in cancer it has been investigated in others cancer histotypes, mainly by qPCR." (PMID 31582772, 2019). "Polyinosinic-polycytidylic acid (poly I:C), ligand of TLR3, mediates innate immune and adaptive immune and shows broad antitumor effect on many types of cancer." (PMID 31058074, 2019). "In our study, the observed anti-tumoral effects, in particular the induction of a type I-interferon response, after targeted delivery of Riboxxol substantiates TLR3 agonists as promising candidates for cancer immunotherapy." (PMID 30824859, 2019). "Taken together, these results indicate that single inhibition of either cIAPs or c-FLIP can sensitize cancer cells to TLR3-mediated, RIPK1/caspase-8-dependent apoptosis." (PMID 30158588, 2018). "TLR3 agonists have been utilized to treat cancer patients with the aim of inducing an IFN-mediated anticancer immune response." (PMID 29344432, 2018). "It has been reported that cathepsin B promotes cancer cell migration or invasion through proteolysis of extracellular matrix and activation of Toll-like receptor 3 (TLR3) and uPA." (PMID 29455656, 2018). "The HIV transactivation response (TAR) element RNA in HIV-infected T-cell exosomes is responsible for promoting cancer cell proliferation and inducing expression of proto-oncogenes and Toll-like receptor 3 (TLR3)-inducible genes." (PMID 30389917, 2018). "Remarkably, the release of the c-FLIP, but not cIAPs, brake only results in the sensitization of all human cancer cells to TLR3-mediated apoptosis." (PMID 30158588, 2018). "Conversely, 5 out of 9 (60%) SCLC and 18 out of 30 (60%) SC expressed TLR3 but at a much lower level (median scores of 10 for both, P < 0.0001), indicating that either TLR3 is lost in these types of cancers or that they arise from a different cell of origin." (PMID 30158588, 2018). "Further, these findings indicate a clinical relevance of TLR-3 signaling and its potential for therapeutic applications against cancer by targeting TAMs." (PMID 30072995, 2018). "These cancer cells express PRRs which are able to respond to double-stranded (ds)RNA such as TLR-3, RIG1, MDA5 and PKR." (PMID 30613350, 2018). "In humans, TLR3 agonists have been used as adjuvant treatments for cancer patients with variable success." (PMID 29344432, 2018). "Activation of TLR3 stimulates cancer cell apoptosis and triggers secretion of inflammatory cytokines." (PMID 28427199, 2017). "In contrast, when Tlr3−/− mice were injected with cancer-derived exosomes, the level of spontaneous metastasis was comparable to negative controls." (PMID 28796150, 2017). "In this review, we will discuss the TLR3-mediated signaling in antitumor immunity and its application to cancer immunotherapy." (PMID 29312355, 2017). "The majority of studies of the role of TLR3 in cancer have focused on applying dsRNA analogues in cancer therapy because of their ability to induce growth arrest and apoptosis in some TLR3-expressing tumors." (PMID 28717003, 2017). "We found variations of TLR3 mRNA expression amongst the cancer types tested, and heterogeneity was also observed within the different cell lines of the lung and hepatocellular cancers (HCC)." (PMID 28427199, 2017). "Engagement of polyI:C with TLR3 induces apoptosis and subsequently activates infiltration of immune cells to destroy cancer cells." (PMID 28427199, 2017). "Here, we used polyI:C as a model ligand to delineate the differential outcomes of TLR3-mediated anti-cancer effects." (PMID 28427199, 2017). "IL-6 is a pro-inflammatory cytokine regulated by TLR3 and has been shown to be important for the growth and migration of cancer cells." (PMID 29371911, 2017).